GPS2 (G protein pathway suppressor 2)
Diseases named in the same sentence as GPS2 in open-access papers (continued):
Sharing a sentence is not in itself a finding about the gene and the disease.
metabolic syndrome (1 paper, 2021). A cluster of metabolic risk factors for CARDIOVASCULAR DISEASES and TYPE 2 DIABETES MELLITUS. "A potential connection between metabolic syndrome and the transcriptional repressor G protein pathway suppressor 2 (GPS2) was uncovered, where a defined set of inflammatory genes are repressed by GPS2 protein." (PMID 34358410, 2021).
pancreatic cancer (1 paper, 2025).
peritoneal cancer (1 paper, 2025). A peritoneum cancer that is located in the inside of the abdomen. "Multivariate analysis identified GPS2 (p = 0.006) and the peritoneal cancer index (PCI) (p = 0.029) or the Japanese surgical peritoneal metastasis grade (p = 0.009) as independent poor prognostic factors." (PMID 40607290, 2025).
pulmonary hypertension (1 paper, 2024). Increased pressure within the pulmonary circulation due to lung or heart disorder. "In our study, we observed that CS-exposed rats with overexpressed GPS2 exhibited attenuated interstitial lung lesions, suggesting that GPS2 might play a role in pulmonary hypertension by modulating interstitial lung lesions." (PMID 38755610, 2024).
Right ventricular hypertrophy (1 paper, 2024). In this case the right ventricle is more muscular than normal, causing a characteristic boot-shaped (coeur-en-sabot) appearance as seen on anterior- posterior chest x-rays. "More importantly, CS-exposed rats with GPS2 overexpression had lower right ventricular systolic pressure (RVSP), right ventricular hypertrophy index (RVHI), and wall thickness (WT%) than those without." (PMID 38755610, 2024).
soft tissue sarcoma (1 paper, 2016). A malignant neoplasm arising from muscle tissue, adipose tissue, blood vessels, fibrous tissue, or other supportive tissues excluding the bones. "The present studies expanded our understanding of the function of GPS2 and highlight the importance of GPS2 in tumorgenesis of soft tissue sarcomas." (PMID 27460081, 2016). "In view of that GPS2 is downregulated in the adipose tissue of obese individuals and that it plays a critical role in the regulation of adipose tissues, we attempt to explore the potential role of GPS2 in LPS, the most common subtypes of soft tissue sarcoma." (PMID 27460081, 2016).
type 2 diabetes (1 paper, 2020). "Our findings thereby strengthen the involvement of GPS2 in regulating transcriptional cascades in human adipocytes in response to metabolic stress that accelerates the development of type 2 diabetes." (PMID 32798719, 2020). "•GPS2 and ABCG1 levels in omental adipose tissue inversely correlate with type 2 diabetes in obese humans." (PMID 32798719, 2020).
tumor (13 papers, 2010 to 2025). "LAP3, ADRA1D, KIF25, GPS2, and MCF2L genes were associated with proliferation, movement, and invasion of tumor cells." (PMID 39839768, 2024). "All mice developed primary tumors on both sides, with GPS2 null cells leading to significantly enlarged tumor size (nearly 30%) in comparison to matched WT-derived tumors." (PMID 33490071, 2020). "In conclusion, our studies identify GPS2 functions as a tumor suppressor in LPS and its downregulation is correlated to prognosis of LPS." (PMID 27460081, 2016). "In this study, we reported that GPS2, a small transactional cofactor, functioned as a tumor suppressor in LPS." (PMID 27460081, 2016). "Most tumour suppressor genes displayed classic mutation/LOH associations, including PTEN and 10q23.1 deletion (OR=3.4; 95% CI=1.7–6.6), and GPS2 and 17p13.1 deletion (OR=7.1; CI=2.3–29)." (PMID 27161491, 2016). "qPCR analysis showed that the mRNA levels of GPS2 were significantly lower in tumor samples than their normal control." (PMID 27460081, 2016). "Our results indicated that GPS2 act as a tumor suppressor in LPS and it may serve as a prognosis marker in this disease." (PMID 27460081, 2016). "Conclusively, our results suggest that GPS2 may act as a tumor suppressor in LPS and serve as a potential prognosis marker for this disease." (PMID 27460081, 2016). "GPS2 and GPS2P1 are uncorrelated in normal tissue but are correlated in primary tumor samples achieving a significantly higher correlation in tumor tissue (Fisher’s r to z transformation p-value < 0.0001)." (PMID 32241256, 2020). "We found that GPS2-deleted MDA-MB-231 cells exhibited increased proliferative, migratory, and invasive properties in vitro, and conferred greater tumor burden in vivo in an orthotopic xenograft mouse model." (PMID 33490071, 2020).
cancer (4 papers, 2019 to 2025). A tumor composed of atypical neoplastic, often pleomorphic cells that invade other tissues. "Exactly, previous studies have shown that PRPF8, SPAG7, SENP3 and GPS2 are associated with the occurrence of various cancers." (PMID 40015977, 2025). "Moreover, future studies confirming the extent of metabolic reprogramming associated with the loss/downregulation of GPS2 across different cancer types may also suggest alternative combination therapies that exploit specific metabolic vulnerabilities." (PMID 33490071, 2020). "In this light, modulation of ubiquitination activity by GPS2 can function as a key determinant in controlling cancer progression, thus underscoring its potential as a targeted therapeutic avenue for intervention." (PMID 40305047, 2025). "However, molecular mechanisms by which GPS2 prevents cancer development and/or progression are largely unknown." (PMID 33490071, 2020). "However, a mechanistic understanding of GPS2 role in cancer is currently lacking." (PMID 33490071, 2020).
infection (2 papers, 2020 to 2021). The state of being infected such as from the introduction of a foreign agent such as serum, vaccine, antigenic substance or organism. "Then, we infected siRNA-treated cells grown in 24-well plates with IAV at a multiplicity of infection (MOI) of 0.01 to evaluate the effect of GPS2 knockdown on IAV replication." (PMID 33658351, 2021). "Infection with the virus shortened the half-life of GPS2 to ∼16 h, suggesting that IAV infection promoted the protein degradation of GPS2 in the cells." (PMID 33658351, 2021).
CNS tumor (1 paper, 2009). "In the CNS tumor dataset, some significant genes like GPS2, beta-NAP, KIAA0220 gene, NSCL1 etc., are identified." (PMID 19718448, 2009).
metabolic disease (1 paper, 2023). A congenital disorder (due to inherited enzyme abnormality) or acquired (due to failure of a metabolically important organ) disorder resulting from an abnormal metabolic process. "Because GPS2 expression, and thereby corepressor complex function, in tissue macrophages is altered in immuno-metabolic disease contexts in humans, our study should stimulate the further investigation of IL4 signaling in human macrophage subtypes." (PMID 36610795, 2023).
GPS2 also shares sentences with these, for which no sentence is quoted: Insulin resistance (3 papers); diabetes (2); anaplastic large cell lymphoma (1); cervical cancer (1); invasive breast carcinoma (1); liver cancer (1); mitochondrial disease (1); myeloid neoplasm (1); osteosarcoma (1); Pituitary adenoma (1); Rett syndrome (1); Thrombocytopenia (1).